TSC2 (TSC complex subunit 2)
Diseases named in the same sentence as TSC2 in open-access papers (continued):
Sharing a sentence is not in itself a finding about the gene and the disease.
cancer (continued). "As in fibroblasts, GSK3 modulates TSC1/TSC2 complex via phosphorylation mechanisms in cancer cells." (PMID 25273085, 2014). "The significance of these complex biochemical signaling events is that cancer cells that overexpress activated Akt or lack PTEN/TSC1/TSC2 expression have an Achilles heel with regards to therapeutic intervention as they are highly sensitive to rapamycin treatment." (PMID 23006971, 2012). "It is possible that an inhibitor of TSC2 can be used in conjunction with drugs that target deregulated oncogenic activation to decrease the development of resistant cancers and achieve a better clinical outcome in Rb mutant cancers." (PMID 20706560, 2010). "To test whether inactivation of TSC2 can be used to specifically kill Rb mutant cancers, we used lentivirus to express short hairpin RNA specific to TSC2 (shTSC2) in Rb mutant and Rb wild type cancer cells." (PMID 20706560, 2010). "Cancer growth in bone requires the activation of various signaling pathways in cancer cells and stromal cells, including those stimulated by TGF-β and RANKL and mediated through Src tyrosine kinase, mTOR signaling mediated by mutations in TSC2 and the Wnt/β-catenin pathway." (PMID 36005209, 2022). "Furthermore, AMPK phosphorylates TSC2 and Raptor, and inhibits mechanistic target of rapamycin (mTOR) complex 1 (mTORC1), which is often aberrantly activated in cancer cells and therefore a promising target for cancer therapy." (PMID 33919842, 2021). "Therefore, we suggest that agents that can modulate cellular stress, such as an activator of AMPK or inhibitors of lipid synthesis, could potentially enhance the killing of Rb mutant cancer cells by inhibiting TSC2." (PMID 20706560, 2010). "In addition, since apoptosis induced by shTSC2 in Rb mutant cells is affected by Bcl-Xl levels, inhibitor of Bcl-2 family of proteins, such as ABT-263 or ABT-737, could also increase the efficacy of TSC2 inhibitor induced killing of Rb mutant cancers." (PMID 20706560, 2010). "Therefore, inactivation of TSC2 and chemothereputics that result in induction of cellular stress may be a novel and effective way to treat cancers containing inactivated Rb." (PMID 20706560, 2010). "Inactivating human Tsc2 in cancer cells inhibits RB1 mutant cell growth, indicating potential therapeutic strategies for RB1-inactivated cancers." (PMID 39000021, 2024). "Here, we describe a novel multiprotein complex (DockTOR) essential for the survival of cancer cells under stress, triggered by the GTPase Cdc42 and a signaling partner Dock7, which includes AKT, mTOR, and the mTOR regulators TSC1, TSC2, and Rheb." (PMID 36711811, 2024). "The relative lack of cancer-associated inactivating TSC2 mutations may result from the increased nutrient sensitivity associated with TSC2 loss and the inability of cells with TSC2 mutations to reconcile the metabolic needs for anabolic growth with nutrient availability." (PMID 38117060, 2024). "In contrast, its overexpression increases phosphorylation and activity of both TSC1 and TSC2, whereas increased phosphorylation of S6K1 and 4E-BP1 is observed in DYRK1A knockdown cancer cells—the effect inhibited by the mTOR-inhibiting drug rapamycin." (PMID 36982355, 2023). "We emphasize that early targeted genetic testing is a priority if TSC2/PKD1-CGS is suspected; extended MLPA or NGS is necessary for affected children with early onset or recurrent malignant tumors." (PMID 36979978, 2023). "It has been reported that most of the 8 ARGs (VIM, UFM1, TSC2, SRC, MEFV, CTTN, CFTR and CDKN1A) are related to cancer." (PMID 35121801, 2022). "AKT activation leads to cell growth by activating mTOR through TSC1/2 phosphorylation, while increased levels of TSC1/TSC2 inhibit the mTOR pathway; mTOR positively regulates 4E-BP1 and p70S6k, which are activated in a variety of cancers." (PMID 33805447, 2021).
cancer (continued). "In general, activated AKT promotes cancer development via phosphorylation and inhibition of the three key downstream effectors, GSK3, TSC2, and FOXO." (PMID 34621748, 2021). "Gene expression profile analysis from the NanoString Cancer Metabolism panel showed a significant decrease in ODC1 and an increase in TSC2 mRNA expression in LCC9 xenografts when these were co-treated with CB-839 and everolimus." (PMID 31428575, 2019). "Blocking REDD1 or TSC2 expression by RNAi leads to the stimulation of mTOR signaling and to the emergence of senescent HPV-positive cancer cells under hypoxia." (PMID 28678198, 2017). "Collectively, these data argue that the hypoxic impairment of mTOR signaling, which occurs at least in part via the inhibitory REDD1/TSC2 axis, enables HPV-positive cancer cells to evade senescence under conditions of E6/E7 repression." (PMID 28678198, 2017). "The phosphorylation and the inhibition of TSC2 by AKT is the earliest link between mTORC1 and a pathway dysregulated in cancer." (PMID 26536660, 2015). "This phosphorylation of AMPKα appeared to be enzymatically inactive in relation to TSC2, ACC, and mTOR phosphorylation but still seemed able to promote cancer cell survival." (PMID 25798539, 2015). "We expected that phosphorylation of TSC2 or ACC would correlate with p-AMPK after treatment with wild-type PKR in H1299, A549, and H322 cancer cells." (PMID 25798539, 2015). "Positive growth signal from RAS-MAPK pathway inhibits TSC2, although the phosphorylation and inhibition of TSC2 by AKT are the clearest links between mTORC1 and pathway deregulation in cancer." (PMID 26536660, 2015). "In cancer cell lines, AMPK activators, such as metformin, can significantly inhibit cell growth by induction of cell cycle arrest through AMPK activation, and this effect may be associated with suppression of anabolism through inhibition of mTOR by phosphorylating tuberous sclerosis 2 (TSC2)." (PMID 25244018, 2014). "These deletions contained known cancer genes based on the Sanger Census cancer gene list, including FGFR3, RECQL4, NOTCH1, PTEN, TSC2, and/or ASPSCR1 which suggested their roles as tumor suppressor genes in the development of HCC." (PMID 25469175, 2014). "Our previous studies have shown that inactivation of Rb and TSC2, a negative regulator of TORC1, induced synergistic cell death in cancer cells through induction of excessive cellular stress, including oxidative stress." (PMID 24809668, 2014). "Additionally, genes such as TSC2, FAM134C, USP36, TECPR1, and LRSAM1 are involved in pathways including macroautophagy and selective autophagy, which can contribute to cancer when dysregulated." (PMID 40279344, 2025). "For example, the insulin-lowering effect of metformin is thought to contribute to its anti-cancer activity, which suggests that patients with hyperinsulinemia or tumors expressing the insulin receptor, LKB1, or TSC2 may benefit most from metformin." (PMID 35631452, 2022). "Although the TSc2 gene Eker-infected mouse model has a highly inherited cancer, the role of TSC1 and TSC2 in RCC in some individuals is unknown." (PMID 36447689, 2022). "Most of the mutations of MET, TSC2, and RB1 that were detected in cohort 1 of this study were private and would therefore not qualify for a broadly applicable “off-the-shelf” cancer vaccine or ACT approach." (PMID 32228647, 2020).
cancer (continued). "First, patients with TSC2/PKD1 CGS have high mutation burden and produce several neoantigens, which are produced by cancer cells that have not been previously recognized by the immune system." (PMID 31870441, 2019). "Conversely, we identified germline alterations in TSC2 and HRAS in two of our patients, with no pathogenic or likely pathogenic germline variants in those genes identified in the PHTS component cancers within TCGA." (PMID 29684080, 2018). "Different to cancer cells, no significant cell death effect was found in VSMCs after knockdown of Rb and TSC2." (PMID 28076433, 2017). "Knockdown of TSC2 induced synergistic cell death which was different in cancer cells, as no significant cell death effect was found in vascular smooth muscle cells after knockdown of TSC2." (PMID 28387735, 2017). "To determine whether the dual inhibition of mTORC1 and TGM2 could induce cancer cell apoptosis, we analyzed PI and ANNEXIN V staining of tsc2-/- MEF cells by flow cytometry." (PMID 26872016, 2016). "Notably, of the eight cancer-related genes, six (TSC1, TSC2, PIK3CA, IGF1R, PDPK1 and AKT2) are known longevity related genes according to GenAge database in human/model organisms, and genetic manipulation of these genes can directly lead to shortening or extending lifespan of model organisms." (PMID 37582720, 2023). "Furthermore, GEPIA correlation analysis showed a negative correlation between TSC2 and Glrx in cancers, suggesting a potential contribution of Glrx in the development of LAM." (PMID 37478294, 2023). "Early on, metformin’s role in cancer clearly showed that AMPK-dependent inhibition of mTOR is required for multiple anti-cancer effects, as the phenotype can be rescued by targeting AMPK with siRNA or Compound C as well as constitutive activation of mTOR and short hairpin RNA targeting TSC2." (PMID 35631452, 2022). "In addition, analyzing data from The Cancer Genome Atlas, the expression profiles of HRH1 and TSC2 were found to be negatively correlated (PCC = −0.15, P = 2 × 10‐6) and, conversely, HRH1 expression was found to be positively correlated with the canonical lung‐metastasis signature and mTOR pathway." (PMID 34378323, 2021). "It is likely that in addition to TSC2, SGK3 will phosphorylate a group of Akt substrates that could play important roles in driving metabolic, transcription and translational responses needed for the survival and proliferation of cancer cells." (PMID 27481935, 2016). "In addition, we also found that a set of 730 CpG sites located within the epi-driver genes had the same direction of change for three or more cancer subtypes, including genes that had previously proved to have biological functions in cancer progression such as EGFR, NCOR2, MAML3, TSC2, and FGFR2." (PMID 35069697, 2021). "We did not detect any expression change of TSC2, ACC, and mTOR phosphorylation in these cancer cells after induction of PKR." (PMID 25798539, 2015). "To our surprise, we did not detect any change in the phosphorylation of TSC2, ACC, or mTOR in H1299, A549, and H322 cancer cells after inducing PKR." (PMID 25798539, 2015). "However, high levels of MMP-7 have been described in several types of invasive cancers, and the role of MMP-7 in mediating invasive capability in a dependent β-catenin way was reported in nonadherent Eker rat Tsc2−/− cells." (PMID 34944575, 2021). "In this study, CPT could activate TSC2 when activates AMPK, but has no activation of raptor, clarifying that a TSC2-dependent mechanism was triggered by CPT in cancer cells." (PMID 28061838, 2017).
genetic disorder (41 papers, 2007 to 2026). "Tuberous sclerosis complex (TSC) is a genetic disorder caused by mutations in either the TSC1 or TSC2 genes." (PMID 41255962, 2025). "The TSC2/PKD1contiguous gene syndrome is a rare genetic disorder caused by a large deletion on chromosome 16p13.3 that simultaneously affects theTSC2 and PKD1 genes." (PMID 40822828, 2025). "TSC is a genetic disorder with an incidence of 1 in 6000 people worldwide caused by mutations in the TSC1 or TSC2 genes." (PMID 38255309, 2024). "Tuberous sclerosis complex (TSC) is a genetic disorder caused by a heterozygous mutation in either of the genes TSC1 at 9q34 (encoding hamartin) or TSC2 at 16p13.3 (encoding tuberin), affecting one in 6000 live births." (PMID 36615165, 2023). "TSC1 and TSC2 genes were named because some of their mutations are related to a genetic disorder TSC." (PMID 37990318, 2023). "Tuberous sclerosis (TSC) is a genetic disorder caused by mutation of the TSC1 or TSC2 genes, encoding two crucial proteins: TSC1 (hamartin) and TSC2 (tuberin)." (PMID 36430972, 2022). "Tuberous sclerosis complex (TSC) is a rare genetic disorder caused by a mutation of TSC1 or TSC2 and characterized by the multisystemic growth of tumor‐like lesions called hamartomas." (PMID 29881807, 2018). "Tuberous sclerosis complex (TSC) is a multisystem genetic disorder caused by mutations in TSC1 or TSC2." (PMID 29881807, 2018). "Tuberous Sclerosis Complex (TSC) is a rare genetic disorder that results from a mutation in the TSC1 or TSC2 genes leading to constitutive activation of the mechanistic target of rapamycin complex 1 (mTORC1)." (PMID 28808237, 2017). "Tuberous sclerosis complex (TSC) is a genetic disorder caused by heterozygous inactivating mutations of either the TSC1 or TSC2 gene." (PMID 26693177, 2015). "Tuberous sclerosis complex (TSC) is a genetic disease resulting from mutation in TSC1 or TSC2 and subsequent hyperactivation of mammalian Target of Rapamycin (mTOR)." (PMID 26220190, 2015). "A rare genetic disorder, known as TSC-2/PKD-1 contiguous gene syndrome, occurs when a large deletion on chromosome 16 affects boththe TSC2 and PKD1 genes." (PMID 40822828, 2025). "Mutations in the TSC1 and TSC2 genes lead to dysfunctional mTOR signaling and cause tuberous sclerosis complex (TSC), a genetic disorder that affects multiple organ systems, principally the brain, heart, skin, and kidneys." (PMID 38534508, 2024). "Tuberous sclerosis complex (TSC) is a genetic disease that arises from TSC1 or TSC2 abnormalities and induces the overactivation of the mammalian/mechanistic target of rapamycin pathways." (PMID 35359647, 2022). "Tuberous sclerosis complex (TSC) is a multisystem genetic disorder caused by pathogenic variants in TSC1 and TSC2 genes." (PMID 36238691, 2022). "We further extended our findings to another genetic disorder with high co-morbidity with ASD, TS, caused by mutations in either of two distinct and independent genes—hamartin (TSC1) or tuberin (TSC2)." (PMID 26393489, 2015). "This rare, multisystem genetic disease results from mutations from one of two genes, TSC1 or TSC2." (PMID 26998374, 2016). "In terms of treatability, TSC1-, TSC2-, SLC35A2-, ATP7A-, ALDH7A1-, and MMACHC-related disorders had specific therapeutic regimens and accounted for 18.5% (19/103) of the cases with genetic disorders." (PMID 35330882, 2022).
benign tumors (21 papers, 2012 to 2026). "The primary cause of TSC is mutations in the TSC1 (hamartin) or TSC2 (tuberin) genes, leading to dysregulation of the mTOR signaling pathway and the formation of benign tumors." (PMID 40364023, 2025). "Germline mutations in TSC1 or TSC2 genes cause benign tumors in multiple organs in patients with TSC." (PMID 29491408, 2018). "Mutations in TSC1 or TSC2 are also associated with tuberous sclerosis complex (TSC), an autosomal dominant disorder characterized by benign tumors in the lungs, kidneys, or heart." (PMID 41465847, 2025). "The Tsc2 heterozygous mouse model employed here displays benign tumors that develop primarily in the liver and kidneys." (PMID 34806651, 2021). "Mutations in either the TSC1 or TSC2 tumor suppressor genes cause TSC, which is a genetic syndrome that leads to manifestation of benign tumors in the brain and other organs such as kidneys, heart, eyes, lungs, and skin." (PMID 29127155, 2017).
infection (16 papers, 2013 to 2025). The state of being infected such as from the introduction of a foreign agent such as serum, vaccine, antigenic substance or organism. "Hence, the observation that HCMV encodes a TSC2 inactivator already provides a clue that Akt activity is either insufficient or missing during infection." (PMID 35946797, 2022). "The SA mutation, by contrast, preserves overall TSC2 functionality and amplifies effector function and proliferation, but it only does so with selective stimulation conditions, which preserves long-term persistence and memory formation when the infection has cleared." (PMID 37788104, 2023). "The results indicated that ORFV infection activated autophagy by mediating the expression of upstream regulators (including TSC2, Rheb and P70S6K) of mTOR and thus inhibiting mTOR expression." (PMID 36918891, 2023). "There were also more SA/SA CD8+ T cells at later time points (6 weeks) after infection when memory formation has taken place, indicating that they retained their ability to persist long-term in striking contrast to TSC2–/– CD8+ T cells." (PMID 37788104, 2023). "As previously shown, TSC2–/– CD8+ T cells respond to an acute infection with greater proliferation in vivo as compared with WT T cells." (PMID 37788104, 2023). "We confirmed the reduction of Chd8 and Tsc2 expression by quantitative RT-PCR after 7 days of infection." (PMID 34497307, 2021). "In contrast, increased macrophage density was only noted in mice with the highest levels of Tsc2 deletion (images from mice with high infection efficiency)." (PMID 31182472, 2019). "In contrast, we observed a substantial reduction in the percentage of Tsc2-expressing neurons 3.5 weeks post-infection in Tsc2 KO-AAV8 mice, with > 50% deletion in most cases." (PMID 31182472, 2019). "Infection of myotubes with an adenovirus expressing TSC2 shRNA (Ad‐TSC2 shRNA) resulted in efficient shRNA‐mediated knockdown of TSC2; the effect was evident after 3 days post‐infection at 4 × 107 PFU/ml." (PMID 28130275, 2017). "To test whether Tsc2 deletion in adult mice induces a pro-regenerative landscape in the DRG, we assessed cJun and Atf3 expression as well as macrophage density in uninjured DRG of control-AAV8 and Tsc2 KO-AAV8 mice 3.5 weeks post-infection." (PMID 31182472, 2019). "We further evaluated endogenous TSC2 interactions with N protein following ANDV infection of MECs." (PMID 27795403, 2016). "Furthermore, TSC2 inactivation actually slightly inhibited both WT and ΔUL38 infection." (PMID 38117060, 2024). "However, at day 300 after infection, there were far fewer memory TSC2–/– CD8+ T versus controls." (PMID 37788104, 2023). "Following infection with duck enteritis virus (DEV), siRNA can regulate autophagy by targeting AMPK or TSC2, thereby affecting the AMPK-TSC2-MTOR signaling pathway." (PMID 40842844, 2025). "In Tsc2 KO-AAV8 mice, we observed 61.0 ± 5.9% of all L4 DRG neurons expressed GFP as a result of AAV8-Cre infection." (PMID 31182472, 2019). "Adult deletion of Tsc2 induced an upregulation of cJun-positive and Atf3-positive nuclei with a correlation between the amount of RATF-positive neurons and infection efficiency." (PMID 31182472, 2019). "We found that the amount of phosphorylated TSC2 increased in wild type-infected cells (lane 2) but not in Y89F-infected cells (lane 4) at 4 h post-infection." (PMID 30619194, 2018). "pUL38 interacts with TSC2, a component of the tuberous sclerosis tumor suppressor protein complex (TSC1/2), to maintain an active mTOR pathway during infection, whereas pUL29/28 was not shown to associate with TSC2." (PMID 23807710, 2013). "Unlike expression of RATFs and macrophage density, increased infection efficiency did not correlate with increased axon length in Tsc2 KO-AAV8, suggesting that mTORC1 activation in a relatively low number of neurons is sufficient to observe enhanced axon growth at 3 d post-injury." (PMID 31182472, 2019).